SNORD113-1 (small nucleolar RNA, C/D box 113-1)
Synonyms: 14q(I-1)
Gene: Small nucleolar RNA gene on chromosome 14 (100,924,824 to 100,924,892, forward strand). Ensembl gene ENSG00000202191.
Gene Ontology:
Biological process: RNA processing
Cellular component: nucleolus
Homologues: Orthologues: chimpanzee SNORD113-1 (100% identical). Paralogues in human: SNORD113-9 (74% identical), SNORD113-6 (72% identical), SNORD113-3 (71% identical), SNORD113-7 (70% identical), SNORD113-8 (67% identical), SNORD113-4 (65% identical), SNORD113-5 (65% identical), SNORD114-18 (64% identical), SNORD114-22 (64% identical), SNORD114-23 (64% identical), SNORD114-4 (64% identical), SNORD114-10 (62% identical), and 26 more.
Diseases named in the same sentence as SNORD113-1 in open-access papers:
SNORD113-1 is named in the same sentence as 3 diseases in open-access papers, as found by Europe PMC text mining. Sharing a sentence is not in itself a finding about the gene and the disease. The quoted sentences say what the papers report.
hepatocellular carcinoma (4 papers, 2014 to 2020). A malignant tumor that arises from hepatocytes. "For example, SNORD50 acts as a tumor suppressor in prostate and breast cancer, and SNORD113-1 is downregulated in hepatocellular carcinoma (HCC)." (PMID 32977537, 2020). "On the other hand, the tumor suppressive role of the SNORD113-1 gene has been confirmed in hepatocellular carcinoma (HCC)." (PMID 28212545, 2017). "In hepatocellular carcinoma (HCC), SNORD113-1 has been identified as a tumor suppressor." (PMID 26041889, 2015). "The roles of small nucleolar RNA 113–1 (SNORD113-1) on the development of hepatocellular carcinoma (HCC) remain unknown." (PMID 25217841, 2014).
tumor (2 papers, 2014 to 2018). "In the present study, we demonstrated that small nucleolar RNA 113-1(SNORD113-1) was significantly downregulated in HCC tissues as compared with adjacent non-tumor tissues, and this downregulation of SNORD113-1 was associated with decreased survival of HCC patients." (PMID 25217841, 2014). "In addition, the results from a xenograft animal model provided the direct evidence that SNORD113-1 can regulate HCC tumor cell growth and that the loss of SNORD113-1 gene function may be directly associated with tumor development." (PMID 25217841, 2014). "In the present study, downregulation of SNORD113-1 was frequently observed in HCC tumors but rarely present in non-tumor tissues." (PMID 25217841, 2014). "These exciting findings suggest that SNORD113-1 may play a role as a tumor suppressor gene." (PMID 25217841, 2014).
cancer (1 paper, 2014). A tumor composed of atypical neoplastic, often pleomorphic cells that invade other tissues. "In addition, overexpression of SNORD113-1 could inhibit cell viability and proliferation of cancer cells, and thus have an important role in the development of HCC." (PMID 25217841, 2014).